TF (transferrin)
Diseases named in the same sentence as TF in open-access papers (continued):
Sharing a sentence is not in itself a finding about the gene and the disease.
malnutrition (continued). "Although albumin, transferrin, and total cholesterol are dependent on several factors, low serum levels together with reduced ingestion, weight loss, and low BMI inferred a significant prevalence of malnutrition at baseline (N = 12; 40%)." (PMID 38201958, 2023). "We hypothesized that malnutrition-induced low transferrin levels in AN might cause IOL and hepatic injury." (PMID 37907890, 2023). "In contrast, in adult patients undergoing joint arthroplasty or hip fracture surgery, malnutrition defined by serologic markers (e.g. albumin, lymphocyte count, transferrin) was predictive for a higher risk of postoperative outcomes, such as wound complications." (PMID 32586289, 2020). "In simple linear regression analysis, we found that log SCL were positively associated with HD vintage, hemoglobin and serum creatinine levels, but negatively associated with age, body mass index, DM, malnutrition status, log ferritin level, and transferrin saturation (p < 0.05)." (PMID 31382911, 2019). "The association between FID and malnutrition verified by the observation of lower BMI, albumin, transferrin, waist circumference, and mid-upper arm circumference in this group seemed to indicate that protein-energy malnutrition might have been a factor." (PMID 31441929, 2019). "Besides the risk screening tools named above, blood markers for malnutrition like albumin, total leucocyte count and transferrin are in controversial discussion." (PMID 29544497, 2018). "Thus, the markedly reduced transferrin levels observed in the discussed patient may hint at malnutrition, protein deficiency, zinc deficiency, chronic liver injury or conditions, such as acute phase reactions, chronic disease or hereditary hypotransferrinemia." (PMID 32468113, 2020). "Short survivors had significantly lower mean albumin (3.1 vs. 3.5 g/dL, p < 0.001), transferrin (156.6 vs. 186.6 mg/dL, p < 0.001) and total cholesterol levels (151.2 vs. 164.0 mg/dL, p = 0.003), indicating a possibly more pronounced state of malnutrition." (PMID 40077616, 2025). "Although serum transferrin levels decrease in cases of severe malnutrition, it has been shown to be an unreliable marker for mild malnutrition and for evaluating lean body mass in older patients." (PMID 41515189, 2025). "Preoperative malnutrition was defined as a total lymphocyte count < 1,500 cells/mm3, a serum albumin concentration < 3.5 g/dL, or a transferrin concentration < 200 mg/dL within the six months before surgery." (PMID 40727701, 2025). "According to transferrin levels, malnutrition was demonstrated in 49% of subjects, according to albumin levels in 71.8% of subjects, and according to prealbumin levels, 76.5% of subjects were malnourished." (PMID 40612307, 2025). "Given the high prevalence of nutritional deficiencies in HIV-CHF patients, serum levels of vitamin B12, folate, and iron studies (serum ferritin, transferrin saturation, total iron-binding capacity) are crucial." (PMID 40901202, 2025). "As a result, the study demonstrated a strong link between low transferrin levels (< 2.15 g/dL to 3.80 g/dL) and malnutrition, with 97.7% of HD patients falling into one of the malnutrition groups." (PMID 38712760, 2024). "Subsequently, serum albumin and transferrin became highly utilized markers of malnutrition for hospitalized patients." (PMID 38379550, 2024). "Renewed focus on the use of suitable biochemical markers of malnutrition resulted in the recommendation of serum transthyretin, otherwise known as prealbumin, as a more sensitive nutrition marker than albumin and transferrin due to its shorter half-life." (PMID 38379550, 2024). "Biochemical markers, such as total protein, albumin, urea, creatinine, transferrin, and total lymphocyte count, offer insights into the intricate metabolic and immunological aspects of malnutrition." (PMID 38313408, 2023). "The levels of transferrin, which is responsible for serum iron transport, also provide information about the severity of malnutrition." (PMID 37111024, 2023).
malnutrition (continued). "Among proteins, albumin and transferrin, for example, play an important role in the assessment of malnutrition." (PMID 37111024, 2023). "Advanced age (>60 years), high NLR (≥2.62), low transferrin level (<200 mg/dL), low PhA (<4.5°), and low BFP (<10%) are risk factors for CKD malnutrition." (PMID 37299602, 2023). "Identified low values of anthropometric and biochemical parameters, such as BMI, TS, MAMC, total protein, albumin, urea, creatinine, transferrin, and overall lymphocyte count, indicate the presence of first-degree malnutrition in ALS patients." (PMID 38313408, 2023). "Total iron-binding capacity (TIBC), an indirect measure of transferrin, is an independent predictor of malnutrition in HD patients." (PMID 37143004, 2023). "Transferrin has a half-life of approximately 10 days, shorter than albumin and longer than prealbumin, and has been used as a biomarker to evaluate malnutrition status." (PMID 36771359, 2023). "Catabolism and malnutrition can reduce serum transferrin disproportionately to serum iron, leading to elevations in TSAT." (PMID 37623532, 2023). "Decreased transferrin and total cholesterol was observed only in patients with malnutrition according to the GLIM criteria." (PMID 35158762, 2022). "Serum transferrin and hemopexin often decline together during acute-phase reactions and malnutrition." (PMID 36430211, 2022). "Malnutrition in the elderly can become evident via serum proteins such as: (a) pre-albumin, (b) albumin, (c) transferrin, and (d) retinol-binding protein (RBP)." (PMID 35892736, 2022). "In a laboratory test, malnutrition is defined as follows: albumin concentrations <3.5 mg/dl, total lymphocyte count <1,500/mm3, or serum transferrin concentrations <200 mg/dl." (PMID 36684164, 2022). "Lower levels of prealbumin, transferrin, IGF-1 and leptin are known to be associated with malnutrition and as expected, levels of these markers increased following nutritional intervention." (PMID 35334853, 2022). "Serum protein levels (albumin, prealbumin, transferrin, and retinol-binding protein) alone cannot be used as an indicator of malnutrition, as their production is influenced by hepatic disease, sepsis, inflammation, and hydration status." (PMID 34444944, 2021). "On the other hand, our attention was on malnutrition, and hence, we estimated the levels of albumin, total protein, transferrin, and prealbumin." (PMID 32490516, 2020). "The final analysis, also including 62 autologous transplanted patients (total number 100) identified lower albumin, total proteins, and transferrin as useful biomarkers for malnutrition, worsening of performance status, and mucositis onset." (PMID 33488571, 2020). "Transferrin and hemopexin are involved in the transport and storage of iron, and they often decline together with albumin during acute-phase reactions and malnutrition." (PMID 32472529, 2020). "The study by Yi et al26 is the only study that describes malnutrition as low albumin or transferrin or TLC in the second half of the study." (PMID 33939393, 2020). "The study by Huang et al14 is the only study that describes malnutrition as low albumin or transferrin in the second half of the study." (PMID 33939393, 2020). "The levels of albumin, prealbumin, total protein, and transferrin before and after treatment were used for assessing malnutrition." (PMID 32490516, 2020). "One article isolated TLC and one article isolated transferrin as markers for malnutrition, with a maximum study cohort size of 3111." (PMID 33939393, 2020). "Other studies reviewing and/or defining malnutrition by low transferrin, total lymphocyte count or albumin also describe the following associated complications in arthroplasty: wound complications, extended length of stay and periprosthetic joint infection." (PMID 29544497, 2018).
malnutrition (continued). "As for other blood biomarkers, including transferrin, creatinine, total triglycerides, iron, and % hematocrit, we do not find sufficient evidence to support their use as a marker of malnutrition." (PMID 28771192, 2017). "A further aim was to determine the criterion validity with respect to biochemical markers of malnutrition such as serum albumin, transferrin, cholesterol and lymphocytes, the body mass index and the mini nutritional assessment." (PMID 27708835, 2016). "The aim of this study was to evaluate the effect of acute malnutrition on glycosylation by investigating the possible changes in transferrin isoform pattern in malnutrition and its relationship to the severity of malnutrition in children." (PMID 25562020, 2014). "Among all the women, only one case presented a state of severe malnutrition (transferrin less than 100 mg/dl), and among the 4 malnutrition cases in men according to this criterion, 75% had mild to moderate malnutrition and 25% had severe malnutrition." (PMID 23338736, 2012). "Using transferrin serum levels, malnutrition was identified in 7.3% of the sample." (PMID 40727701, 2025). "Additionally, we utilized the three most recognized laboratory parameters for malnutrition—albumin, transferrin, and lymphocytes—enabling evaluation of each criterion's individual and combined effectiveness." (PMID 40727701, 2025). "On the other hand, decreased transferrin levels in a catabolic or malnutrition context may falsely elevate TSAT levels." (PMID 39200886, 2024). "A recent study also reported that serum transferrin and prealbumin may outperform albumin in identifying patients with esophageal cancer with malnutrition and poor prognosis." (PMID 38438901, 2024). "However, serum Fe, ferritin, and transferrin saturation, used to guide Fe replacement, are far from optimal, as they can be influenced by malnutrition and inflammation." (PMID 39121099, 2024). "Additionally, catabolism and malnutrition can reduce serum transferrin disproportionately to serum iron, leading to elevations in TSAT." (PMID 37623532, 2023). "Serum transferrin concentrations are decreased in conditions of severe malnutrition." (PMID 36771359, 2023). "Transferrin expression is also affected by inflammation and malnutrition in the blood." (PMID 35804884, 2022). "When malnutrition is severe, serum transferrin levels decline." (PMID 35892736, 2022). "Because, transferrin synthesis is suppressed under inflammatory conditions and by malnutrition, transferrin saturation (TfS) may in some circumstances appear normal." (PMID 34835988, 2021). "In these cases, most commonly in the context of acute or chronic inflammatory states and the malnutrition-inflammation-atherosclerosis syndrome, transferrin saturation and reticulocyte count are low in the presence of high ferritin levels and are evidence of a lack of metabolic response." (PMID 32188148, 2020). "As compared with the highest quartile group, more subjects in the lowest quartile group were of an older age; had lower hemoglobin and creatinine levels; had a higher prevalence of DM and malnutrition (serum albumin level < 3.6 g/dL); and higher serum transferrin saturation and ferritin levels." (PMID 31382911, 2019). "In addition, since each biomarker has its own characteristic half-life period, such as 10–17 h for RBP, 2–4 days for prealbumin, and 7–10 days for transferrin, it is possible to make a tentative judgment on the duration of malnutrition." (PMID 30355325, 2018). "Pre-albumin and transferrin are impacted by malnutrition and hepatic damage similarly, but respond faster and, therefore, could also be used as early indications of malnutrition." (PMID 29027963, 2017). "In a larger patient group with severe malnutrition and in other disease states with markedly increased catabolism, transferrin isoform analysis with isoelectric focusing may reveal the alterations in protein glycosylation." (PMID 25562020, 2014).
malnutrition (continued). "TIBC may be decreased due to reduced transferrin synthesis in the setting of malnutrition and chronic disease, resulting in high TSAT, disproportionate to the iron content." (PMID 24505281, 2014). "However, TSAT increased when transferrin or TIBC decreased under malnutrition and inflammation." (PMID 36983703, 2023). "It is known that transferrin, the acute-phase reactant protein that transports iron, has been used as well as a marker of nutritional status, given that it parallels prealbumin concentrations during nutritional interventions and is decreased in severe malnutrition." (PMID 36875830, 2023). "However, malnutrition and chronic disease may diminish the synthesis of transferrin, which would raise TSAT." (PMID 33292849, 2020). "Blood indicators of malnutrition included the following routine blood chemistry investigations: Red Blood Cell Count, Hemoglobin, hematocrit, Mean Corpuscolar Volume, Mean Corpuscolar Hemoglobin, Mean Corpuscolar Hemoglobin Concentration, serum Iron, Transferrin, Albumin; Calcium, Phosphorus." (PMID 25000975, 2014). "Since a decrease in the iron-transport protein transferrin presumably increases labile non-transferrin-bound iron, resulting in excess reactive oxygen species production, a defect in iron transport due to malnutrition could be one of the causes of liver injury in AN." (PMID 37907890, 2023). "In conclusion, the present meta-analysis indicated that L-carnitine has a favorable effect on malnutrition biomarkers in patients on MHD, including the increase in the levels of albumin, total protein, transferrin, and prealbumin." (PMID 32490516, 2020). "The present meta-analysis indicated that L-carnitine can have a favorable effect on malnutrition biomarkers in patients on MHD, including the increase in albumin, total protein, transferrin, and prealbumin levels." (PMID 32490516, 2020). "Serum proteins such as albumin and transferrin are classic markers for PEM, and have been considered major indicators of malnutrition." (PMID 33256142, 2020). "Additionally, we studied changes in two other chemical parameters related to malnutrition, namely TIBC as a surrogate for transferrin level, which is included in the malnutrition-inflammation score, and hs-CRP as a surrogate for inflammation." (PMID 37143004, 2023). "Serum transferrin could be measured by using serum TIBC (total iron binding capacity) and is considered as an acceptable marker of malnutrition in patients on MHD." (PMID 35406082, 2022). "Additionally, patients with malnutrition (according to the GLIM criteria) presented with decreased phase angle (PA) and standardized PA (SPA), decreased serum levels of albumin, transferrin and total cholesterol, accompanied by increased serum RCP and IL6." (PMID 35158762, 2022). "Serum IGF-1, transferrin and iron levels, and all transferrin isoform patterns were not significantly different in mildly malnutrition group from other two groups." (PMID 25562020, 2014). "So-called negative APP were uniformly low in children with malnutrition and infection, including transferrin, α-2-HS-glycoprotein, pre-albumin, fibronectin, and α-2-macroglobulin." (PMID 25153531, 2014). "The biochemical parameter of plasma albumin showed that 58.33% of the sample were classified as presenting mild malnutrition, while transferrin showed that 89.58% of the sample was normal." (PMID 23338736, 2012). "It is our view, that with transferrin also being a marker of Iron stores among others, it may not be wise to use it as a determinant of malnutrition – a condition with many facets – on its own." (PMID 38712760, 2024). "Compared to their without malnutrition exposure risk counterparts, the with malnutrition exposure risk group exhibited significantly elevated levels of SHBG and HbA1c and reduced C-peptide, triglycerides, uric acid, hemoglobin, IGF-1, AST, ALT, weight, BMI, albumin, prealbumin, and transferrin." (PMID 39020340, 2024).
malnutrition (continued). "Moreover, transferrin is a known marker of malnutrition in patients with ESRD, but we could not evaluate transferrin as a malnutrition marker." (PMID 26194096, 2015). "Often, they do not have clear signs of malnutrition/PEW according to the standard parameters, such as prealbumin or transferrin levels, and their albumin levels may be modulated more by type of dialysis than by other means." (PMID 32188148, 2020).